BAX (BCL2 associated X, apoptosis regulator)
Diseases named in the same sentence as BAX in open-access papers (continued):
Sharing a sentence is not in itself a finding about the gene and the disease.
leukemia (33 papers, 2011 to 2026). A malignant (clonal) hematologic disorder, involving hematopoietic stem cells and characterized by the presence of primitive or atypical myeloid or lymphoid cells in the bone marrow and the blood. "Appropriate levels of BAX/BAK bound by high levels of BCL-2 indicate a BCL-2 dependence in the leukemia cell, mediating effective cell death induction upon venetoclax treatment." (PMID 40234615, 2025). "induced apoptosis in leukemia versus normal hematopoietic cells, through a process involving Mcl-1 down-regulation, which in turn potentiates BAX activation and mitochondrial translocation, culminating in apoptosis." (PMID 36926328, 2023). "To evaluate the cellular activity of BDM19, we tested its ability to promote apoptotic cell death in various lymphoma and leukemia cell lines expressing either cytosolic BAX monomer (e.g. HPB-ALL) or dimer (e.g. SUDHL-5)." (PMID 38104127, 2023). "We also observed the upregulation of the TNF, TNF receptor member 1 (TNF-R1), and TNF-R member 6 (FAS) genes, and enhanced expression of BAX, an important effector of the extrinsic apoptotic pathway in leukemia cells." (PMID 36294912, 2022). "The high expression of BCL2 and BAX suggests that this otherwise refractory subgroup might display a particular sensitivity to targeted therapy with BH3 mimetics, i.e. BCL-2 bound BAX might act as a suicide bag in this particular type of leukemia." (PMID 40234615, 2025). "Their results showed that McL-1 and BAX could stimulate apoptosis in human leukemia by McL-1 down-regulation, BAX conformational change, and mitochondrial translocation, which resulted in cytochrome C release." (PMID 36926328, 2023). "We also clarified that its leukaemia-promoting effects might function through decreased BAX and cleaved caspase-3 and upregulated bcl-2 levels." (PMID 35534496, 2022). "Indeed, exposure of leukemia, lymphoma and multiple myeloma cell lines to G. pps extract resulted in increased BAX expression and leakage of cytochrome c to the cytoplasm, most likely due to decreased mitochondrial membrane potential." (PMID 34048499, 2021). "Test compounds induced apoptosis in chronic myelogenous (K562) and acute lymphoblastic (MOLT-4) leukemia cells by activation of receptor and mitochondrial apoptotic pathways and increased the expression of proapoptotic genes (BAX, NOXA, HTRA2, TNFRSF10B, ESRRBL1)." (PMID 31487824, 2019). "Similarly to the leukemia, we suppose that there is initiation of apoptosis at least at the level of activated transcription of the BAX gene, but at the same time there is inhibition of apoptosis because of elevated levels of Bcl-2." (PMID 29515335, 2018). "Quercetin induced apoptosis in leukemia cells by decreasing the expression of PI3K and Bcl2 proteins, inhibiting Akt phosphorylation, enhancing BAX protein levels, increasing caspase 2 and 3 activation, and increasing cleavage of poly (ADP ribose) polymerase." (PMID 36926328, 2023).
leukemia (continued). "In CAPE-treated HL-60 leukemia cells, caspase-3 was rapidly activated after 4 h, BCL2 expression decreased after 6 h and BAX expression intensified after 16 h." (PMID 32752091, 2020). "For example, HL-60 cells of human leukemia subjected to the CAPE treatment revealed increased apoptosis by activation of different regulatory elements caspase-3 and BAX regulator and suppression Bcl-2." (PMID 28587155, 2017). "The level of BAX mRNA and the BAX/Bcl-2 ratio in leukemia patient samples were not significantly different to the control group values." (PMID 29515335, 2018). "A silencing approach was used for determining BAG1's role in AML, finding that its down-regulation decreased expression of BCL2, BCL-XL, MCL1, and phospho-ERK1/2, all proteins able to sustain leukemia, without affecting the pro-apoptotic protein BAX." (PMID 22016818, 2011). "Furthermore, it can be exploited to kill leukaemia cells with acquired venetoclax resistance due to lack of active BAX and BAK." (PMID 34931711, 2022). "Moreover, activating endogenous BID can be clinically relevant for therapy to kill venetoclax‐resistant leukaemia cells lacking active BAX and BAK." (PMID 34931711, 2022). "Additionally, we demonstrate the therapeutic potential of tBID‐mediated MOMP in venetoclax‐resistant Nalm6 leukaemia cells lacking active BAX and BAK, in which TRAIL treatment efficiently induces BID‐dependent apoptosis." (PMID 34931711, 2022). "Pro‐apoptotic BCL‐2‐family protein tBID can promote mitochondrial permeabilization not just via BAX/BAK activation, but also on its own to mediate antibacterial responses and apoptosis of venetoclax‐resistant leukaemia cells." (PMID 34931711, 2022).
cervical carcinoma (29 papers, 2002 to 2025). A carcinoma arising from either the exocervical squamous epithelium or the endocervical glandular epithelium. "Overexpression of PRDX1 significantly promoted proliferation and inhibited apoptosis by increasing the expression of Nanog, proliferating cell nuclear antigen (PCNA), B-cell lymphoma-2 (Bcl-2) and downregulating the expression of Bcl2-associated X protein (BAX) in SiHa cervical cancer cells." (PMID 31956363, 2020). "Gold nanoparticles not only directly induce BAX gene expression to induce apoptosis in cervical cancer cells but also form complexes with antibodies as Au@SiO2 nanoparticles for potential therapeutic applications in cervical cancer." (PMID 39845315, 2024). "The combination treatment of cervical cancer cells with crocin and cisplatin promotes antiproliferation and apoptosis by downregulating miR-365a-3p, an upregulator of BAX and BCL2." (PMID 36612314, 2023). "Its depletion in cervical cancer cells can increase the expression of Caspase 3 and BAX, while reducing that of BCL225,46." (PMID 37344615, 2023). "In HeLa cervical cancer cells, luteolin increased the expression of various pro-apoptotic proteins, including BAX, BAD, BID, APAF1, TRADD, FAS, FADD, and caspase-3 and -9, but the expression of anti-apoptotic proteins, such as BCL-2 and MCL-1, decreased." (PMID 36142874, 2022). "BAX is involved in apoptosis, and the expression of BAX is more frequent in NAC responders among cervical cancer patients." (PMID 35736490, 2022). "It has been shown also that knocking down MALAT1 in CaSki cervical cancer cells increased proliferation and invasion rates through BAX up‐regulation." (PMID 33094859, 2021). "There are publications indicating that in cervical cancer, the immunohistochemical expression of BCL2 and BAX is associated with the progression of the disease and the radiosensitivity of tumor cells." (PMID 34830452, 2021). "The PGE2/EP4 pathway is known to suppress apoptosis in cervical cancer cells by preventing the translocation of pro-apoptotic protein BAX into the mitochondria." (PMID 27010855, 2016). "In rectal cancer a significantly higher expression of BAX was observed after preoperative chemoradiation and in cervical cancer increased BAX expression after radiotherapy was related to better tumour control." (PMID 11875737, 2002). "In addition, cervical cancer cell apoptosis was induced through an increase in BAX and a decrease in Bcl-2 in an in vivo tumor model." (PMID 36142874, 2022). "BCL-2 is an anti-apoptotic molecule and the expression of BCL-2 and BAX might correspond to disease stage progression or cell radiosensitivity in cervical cancer." (PMID 34350111, 2021). "miR-886-5p inhibits apoptosis by targeting BAX expression in human cervical carcinoma cells." (PMID 28556798, 2017).
cervical carcinoma (continued). "Specifically, the genes ABL1, BAX, FASN, and PLAU exhibited abnormally high expression levels in cervical cancer specimens, in stark contrast to BCL2, IGF1, and NTRK3, which were markedly under-expressed." (PMID 38988712, 2024). "Expression levels of BAX and BCL2 after radiation therapy are useful prognostic markers in patients with human cervical carcinoma." (PMID 34830452, 2021). "Further investigation in lung and cervical cancer cell lines revealed that DRAM regulates apoptosis by disrupting Bcl-2/BAX interaction, interacting with BAX and directing it to lysosomes, where BAX promotes the release of cathepsin-B." (PMID 33117715, 2020). "Consistent with the previous findings, our study demonstrated that overexpression of PRDX1 significantly promotes cervical cancer cell proliferation, and enhanced the expression of Nanog, PCNA and Bcl-2 and decreased the expression of BAX." (PMID 31956363, 2020). "Using three distinct human cervical cancer cell lines (CaSki [HPV − 16], HeLa [HPV-18], and SiHa [HPV-16]), it was demonstrated that activation of BAX and PARP cleavage were enhanced 48 h after treatment." (PMID 31138113, 2019). "PA-MSHA induced BAD and BAX and inhibited BCL-2, suggesting that PA-MSHA promotes apoptosis in cervical cancer cells by increasing the expression of pro-apoptotic genes and reducing the expression of anti-apoptotic genes." (PMID 27206797, 2016). "Only two genes, the proapoptotic gene BAX and the tumour suppressor gene APC has been found to be consistently downregulated in lymph node metastases and recurrent cervical cancer." (PMID 26551527, 2015). "Although the BAX/BCL-2 ratio remained constant, these findings highlight the potential of SAF as a promising candidate for further study in the development of cancer therapies, particularly targeting cervical cancer HeLa cells." (PMID 37598145, 2023). "The functional role of both genes has been well described in cancer, with the BCL2 homologue gene BAX playing a key role in tumour apoptosis as a proapoptotic gene and APC acting as a tumour suppressor gene, which is frequently inactivated in cervical cancer by hypermethylation." (PMID 17242701, 2007).
glioblastoma (28 papers, 2014 to 2025). The most malignant astrocytic tumor (WHO grade IV). "Therefore, in glioblastoma, inactivating mutations in the BAX gene are considered to be extremely rare, suggesting that domatinostat is a highly promising therapeutic candidate for this tumor type." (PMID 40869124, 2025). "In the anticancer efficacy study of medicarpin on U251 and U87 glioblastoma cells, it was found that medicarpin increased apoptosis in cancer cells by increasing BAX, CYCS and CASP3 gene levels and also decreased Bcl‐2 levels." (PMID 40318008, 2025). "The BCL-2 inhibitor ABT-737 releases pro-apoptotic BAX protein from Bcl-2 and induces apoptosis in glioblastoma cells both in vitro and in vivo." (PMID 35990696, 2022). "Our data show that TIC10/ONC201, when combined with BH3-mimetics, yields a synergistic anti-proliferative and pro-apoptotic effect in a BAX/BAK-dependent manner across different glioblastoma cells." (PMID 26474387, 2015). "Studies have shown that anti-apoptotic Bcl-2 is regulated by ATF5 in glioblastoma cells and BAX is an apoptosis member of the Bcl-2 family." (PMID 25120656, 2014). "Furthermore, allicin potentiates apoptosis in human glioblastoma cells, by elevating the expression of BAX and downregulating BCL2." (PMID 34422220, 2021). "Consistent with this hypothesis, deletion of VDAC2 in glioblastoma cells engineered to be BAX-dependent (i.e., ∆BAK) significantly inhibited apoptosis in response to BH3-mimetics." (PMID 30478310, 2018). "In line with that assumption is our finding that the drug combination of TIC10/ONC201 and ABT263 induces apoptosis in a BAX/BAK-dependent manner since knock-down of BAX/BAK significantly abrogated cell death by the combination therapy in T98G glioblastoma cells." (PMID 26474387, 2015). "2, a subunit of the T-type calcium channel, inhibits glioblastoma growth through suppression of the AKT/mTOR pathway and activation of the BAX-mediated apoptotic pathway." (PMID 40535121, 2025). "We found that BAX, CYCS and CASP3 levels amplified and Bcl‐2 levels reduced in U251 glioblastoma cells to which we applied BA at different doses." (PMID 40318008, 2025). "In support of our findings, new evidence suggests the involvement of the effector caspases 3 and 9, BAX and the phosphor JNK pathway in the AM630 anti-tumoral actions in glioblastoma." (PMID 35408449, 2022). "Immunoblot analysis revealed that the pro-apoptotic markers BAX and cleaved caspase-3 were increased and the anti-apoptotic marker BCL-2 was decreased in BMAL1-overexpressing glioblastoma cells compared with control cells." (PMID 32231148, 2020). "A different mechanism has been observed in glioblastoma cells, in which BAG3 is over-expressed and retains BAX protein in the cytosol, preventing its mitochondrial translocation." (PMID 29487711, 2018). "The present study revealed that HCMV infection blocks apoptosis in glioblastoma U87 cells and increases the expression levels of the ATF5 and Bcl-2 to BAX ratio." (PMID 25120656, 2014). "Apoptotic death in the core of glioblastoma multiforme is triggered by hypoxia and lack of nutrients, with the over-expression of pro-apoptotic BAX (apoptosis regulator), upregulation of CASP3 (caspase-3), and occurrence of internucleosomal DNA fragmentation." (PMID 36838582, 2023). "In the T98G glioblastoma multiforme cell line, the expression of AKT3 or PI3KCA genes is downregulated by siRNAs that target their mRNAs and this leads to the upregulation of the BAX/BCL-2 mRNA expression ratio." (PMID 24967401, 2014). "We observed that the expression of apoptosis-related factors (BIM, BAX and cleaved CASPASE3) and an invasion-related factor (E-CADHERIN) were higher, while the expression of related invasion factors (TWIST1, SNAIL and MMP9) were lower in glioblastoma cells with HDAC1-shRNA infection." (PMID 28624794, 2017).